MMP9 (matrix metallopeptidase 9)
Diseases named in the same sentence as MMP9 in open-access papers (continued):
Sharing a sentence is not in itself a finding about the gene and the disease.
diabetes (continued). "Our findings showed that DCI ameliorated the renal injury induced by diabetes by upregulating MMP-9 and PPAR-γ expression and downregulating NF-κB expression." (PMID 35439732, 2022). "MMP8 and MMP9 aggravate the injury of the knee joint cartilage and promote the apoptosis of articular chondrocytes in diabetes-induced OA rats." (PMID 33468174, 2021). "Of note, the IHC results showed that the number of MMP8- and MMP9-positive cells was significantly increased in the knee joint cartilage of the diabetic OA rats (p < 0.01)." (PMID 33468174, 2021). "The best predictors for 1-year adverse events included elevated levels of I-CAM > 239.7 ng/L and an MMP-9 level of over 1155 ng/mL, respectively, after adjustments for diabetes, hs-CRP, acute phase complications and LVEF for the overall study population." (PMID 34362217, 2021). "In contrast, interfering with the expression of MMP8 and MMP9 alleviated the cartilage damage in diabetic OA rats." (PMID 33468174, 2021). "Aortic and coronary arteries of patients with diabetes taken at autopsy had higher expression of MMP-9 compared to non-diabetes patients and these levels were correlated with HbA1c as well as apoptosis." (PMID 33579197, 2021). "A decline in the expression and activity of MMP‐9 contributes to mesangial matrix accumulation in the diabetic kidney." (PMID 34694755, 2021). "One of the critical MMPs known to be activated in diabetes is MMP-9, the largest and the most complex member which otherwise remains latent in healthy hearts." (PMID 33747350, 2021). "In females, diabetes was associated with elevated GDF-15 and MMP-9, whilst males with diabetes only had elevated GDF-15." (PMID 34526107, 2021). "By inhibiting MMP-2 and MMP-9 with SB-3CT, collagen deposition disorder of the skin in streptozotocin-induced diabetes mice was alleviated." (PMID 34777244, 2021). "MMP-2 and MMP-9 have been shown to contribute to cardiac fibrosis in diabetes and diabetes was found to be enhanced through increased oxidative stress vascular MMP-9 activity." (PMID 33923282, 2021). "Contrarily, exercise exosome enriched with miR-29b and miR-455 lead to downregulation of MMP9 and protect from the detrimental effects of MMP9 such as matrix degradation, fibrosis, and myocyte uncoupling in diabetes." (PMID 34869682, 2021). "During systemic inflammation of systemic diseases such as CVD or diabetes, MMP-9 was mainly synthesized by neutrophils, with increased levels during inflammatory processes, leading to tissue damage to collagen-rich tissue when overproduced." (PMID 33810003, 2021). "Previous studies have shown that matrix metalloproteinase (MMP) 8 and MMP9 were upregulated in patients with diabetic OA." (PMID 33468174, 2021). "MMP9 is a known matrix metalloproteinase (MMPs) released during inflammation and is heavily involved in cardiac fibrosis in diabetes." (PMID 34685620, 2021). "We examined the effect of MMP8 and MMP9 expression intervention on the number of diabetic OA knee chondrocytes." (PMID 33468174, 2021). "In conclusion, our study found that MMP8 and MMP9 are upregulated in the knee cartilage of diabetes-induced OA rats." (PMID 33468174, 2021). "Macrophage migration factor (MIF) and matrix metalloproteinase (MMP-9) are two of the most important factors in the pathogenesis of diabetes." (PMID 34567195, 2021). "Macrophage migration factor (MIF) and matrix metalloproteinase (MMP-9) are the most important factors in the pathogenesis of diabetes." (PMID 34567195, 2021). "The most powerful predictor for MACE was MMP-9 of >1155 ng/mL (AUC-0.786, p < 0.001) even after adjustments for diabetes, LVEF, acute phase complications and other inflammatory biomarkers." (PMID 34362217, 2021). "The imbalance of MMP-2/TIMP-2 and MMP-9/TIMP-1 contributes to the skin disorder of collagen deposition in diabetes patients, providing ideas for managing diabetes skin complications early." (PMID 34777244, 2021).
diabetes (continued). "Diabetes and hypertension lead to structural and functional changes of the neurovascular unit, alter collaterals, and elevate MMP-9, ROS, and proinflammatory cytokines (TNF, IL-1β, and IL-6)." (PMID 34054705, 2021). "MMP-9, depending on the metal ion such as Zn2+and Ca2+, is upregulated during diverse pathologies including arthritis, diabetes, and cancer." (PMID 34336699, 2021). "An overproduction of MMP9 in diabetes causes excessive ECM degradation and results in delayed wound healing, but inhibition or knockout of MMP9 promotes diabetic wound healing." (PMID 32566084, 2020). "In conclusion, by elevating the mitochondria-defender SIRT1 expression and at the same time decreasing the mitochondria-destroyer MMP9 expression in the diabetic eye, BGP-15 is able to counteract the retinal function-deteriorating effect of diabetes." (PMID 32204537, 2020). "MMP-9 has crucial cysteine residues within its DNA-binding domain and the enzyme itself is sensitive to oxidative stress; our previous studies have shown that retinal MMP-9 activation in diabetes can be ameliorated by the regulation of oxidative stress." (PMID 32150828, 2020). "Several studies have also shown that the antidiabetic PPAR-activator rosiglitazone significantly reduces serum MMP-9 levels in type 2 diabetes mellitus patients." (PMID 33082709, 2020). "Their results revealed that GADD45A is essential for MMP-9 promoter demethylation and wound healing in diabetes." (PMID 32695308, 2020). "MMP-9 mediates diabetes-induced retinal neuropathy and vasculopathy and is associated with the severity of diabetic retinopathy." (PMID 33419373, 2020). "Levels of MMPs, especially MMP-9, are known to be influenced by several general conditions such as hypertension, smoking, and diabetes." (PMID 32982940, 2020). "The activation of MMP-9 in diabetes damages retinal mitochondria, releasing cytochrome c into the cytosol and accelerating apoptosis of retinal capillary cells." (PMID 32150828, 2020). "Here, our results show that homocysteine supplementation adds to the diabetes-induced increase in ROS generation, increasing MMP-9 activity and decreasing Timp1 levels and also its interactions with MMP-9." (PMID 32150828, 2020). "In diabetes, the expression of MMP-9 in retina and capillaries is increased, which promotes the development of the disease." (PMID 32695308, 2020). "In diabetes, retinal DNA methylating (DNA methyltransferases, Dnmts) and hydroxymethylating enzymes (ten eleven translocases, Tets) are activated and the MMP-9 promoter undergoes dynamic DNA methylation-hydroxymethylation." (PMID 32150828, 2020). "A close crosstalk between histone methylation, histone acetylation and DNA methylation plays a critical role in the maintenance of cellular epigenetic integrity of MMP-9 in diabetes." (PMID 32695308, 2020). "Homocysteine plays a crucial role in DNA methylation, and in diabetes, the machinery responsible for maintaining DNA methylation status is upregulated and the MMP-9 promoter is hydroxymethylated." (PMID 32150828, 2020). "Consistently with the results from isolated cells, the administration of homocysteine to rats significantly exacerbated diabetes-induced increase in MMP-9 activity and its gene transcripts and further decreased Timp1 transcripts and ROS levels." (PMID 32150828, 2020). "Previous studies showed that overexpression of MMP-9 was involved in the molecular mechanisms of tendinopathy in diabetes." (PMID 30716140, 2019). "MMP-9 has been shown to cleave organ-specific aAg, such as myelin basic protein in multiple sclerosis, collagen in arthritis, insulin in diabetes, and ubiquitous aAg in systemic autoimmune diseases." (PMID 30967870, 2019). "TNF-α, IL-6, and MMP-9 were significantly upregulated in traumatized skin of rats with STZ-diabetes than in normal trauma rats (NC group) (p < 0.05)." (PMID 31605256, 2019).
diabetes (continued). "Elevation of urinary MMP9 activity was found to be related to older age, longer duration of diabetes, high levels of HbA1c and increased blood pressure." (PMID 30396876, 2019). "The detrimental role of MMP-9 was confirmed with MMP-9 knockout mice treated with streptozotocin in order to induce diabetes." (PMID 31121851, 2019). "Propolis extract gel increased the expression of VEGF and decreased that of MMP-9 during the healing process of traumatic ulcers on the oral mucosa of diabetes afflicted Wistar rats (R. norvegicus)." (PMID 29657421, 2018). "The aim of this study was to determine the effect of Apis mellifera propolis extract gel on vascular endothelial growth factor (VEGF) and matrix metalloproteinase-9 (MMP-9) expression in the traumatic ulcers of rats afflicted with diabetes mellitus (DM)." (PMID 29657421, 2018). "Our result accords with the opinion that MMP-9 expression increases significantly in diabetes post-IS." (PMID 29743683, 2018). "An increased circulating concentration of MMP-9 has been demonstrated in patients with obesity, metabolic syndrome, and type 2 diabetes mellitus (T2DM)." (PMID 30035656, 2018). "During diabetes the promoter region of retinal MMP-9 exhibits an upregulation of acetyl H3K9, p65, LSD-1, and a downregulation of H3K9me2." (PMID 30233418, 2018). "A prominent clinical manifestation of MMP-9-induced ECM remodeling is diabetic retinopathy in type 2 diabetes mellitus (T2DM)." (PMID 30149671, 2018). "Understanding the mechanism responsible for the impaired keratinocytes migration in diabetes by characterizing the excessive MMP9 expression mediated by FOXO1 will help set the basis for clinical application of a FOXO1 antagonist in treating diabetic wounds." (PMID 28874756, 2017). "The effect of diabetes on circulating neutrophil MMP-9 and NGAL and the effect of insulin treatment was also studied." (PMID 28182694, 2017). "Despite increased recruitment of DNA methyltransferase 1 (Dnmt1) at the MMP-9 promoter in diabetes, our results have shown that 5 methyl cytosine (5mC) levels are decreased." (PMID 29261844, 2017). "This study aims to investigate link(s) between histone and DNA modifications in the regulation of MMP-9 expression in diabetes." (PMID 29261844, 2017). "MMP-9 promoter has binding sites for many transcription factors, and in diabetes its promoter undergoes epigenetic modifications, including histone modifications and DNA methylation." (PMID 29261844, 2017). "Ezh2 is also directly involved in DNA methylation, and in diabetes MMP-9 promoter undergoes dynamic DNA methylation." (PMID 29261844, 2017). "Keratinocyte-specific deletion of Foxo1 blocked the diabetes-induced increase in MMP9 expression in vivo." (PMID 28874756, 2017). "Altogether, these results provide a novel insight on MMP9-mediated contractile dysfunction in diabetics and opens a new window for future studies for cardiac specific role of MMP9 on contractility in diabetic hearts." (PMID 27014091, 2016). "Elevation of circulating levels of both ET-1 and MMP-9 are observed in patients with cardiovascular diseases, diabetes mellitus and cancers." (PMID 26692905, 2015). "The changes in circulating levels of ET-1 and MMP-9 might be associated with the possible mechanisms such as endothelial dysfunction that might help to explain why people with MetS have a higher chance of developing cardiovascular diseases, diabetes mellitus and cancers." (PMID 26692905, 2015). "Further research is needed to investigate the exact role of ET-1 and MMP-9 in the development of cancer, diabetes and cardiovascular disease in relation to metabolic syndrome." (PMID 26692905, 2015). "Patients suffering from type 1 diabetes mellitus have been demonstrated to have significantly higher abundance of circulating MMP-9." (PMID 26692905, 2015).
diabetes (continued). "High levels of glucose in diabetes upregulates the expression of MMP9 and MMP13 in tendon cells 38 and the elevated MMP9 levels can further lead to cardiac fibrosis and myocyte uncoupling." (PMID 25824442, 2015). "MMP-9 activity has also been shown to be significantly higher in patients with type 2 diabetes mellitus." (PMID 26692905, 2015). "It has been demonstrated that the activities of MMP-9 in plasma and vascular cells are also higher in rodent models of diabetes mellitus." (PMID 26692905, 2015). "As a matter of fact, MMP-9 levels are elevated in patients with emphysema, cancer, diabetes, acute myocardial infarction and other chronic conditions." (PMID 25635861, 2015). "Activity of MMP-9 is highly associated with the progression of CKD, diabetes, and coronary arterial disease." (PMID 26538831, 2015). "Further research is needed to fully dissect the role of ET-1 and MMP-9 in the development of cancers, diabetes and cardiovascular disease in relation to MetS." (PMID 26692905, 2015). "It has been demonstrated that the circulating levels of ET-1 and MMP-9 are higher in patients with diabetes mellitus, cardiovascular diseases, and cancers." (PMID 26692905, 2015). "Here, using in situ zymography and immunostaining we investigated the pattern and cellular origin of glomerular MMP-9 expression and activity in Zucker diabetic fatty rat, an animal model of type 2 diabetes mellitus." (PMID 25849723, 2015). "Uemura reported that diabetes increased the activity of MMP9 via oxidative stress, resulting in increased vascular complications." (PMID 25204377, 2014). "MMP-9 levels were also elevated in patients with diabetes mellitus, and treatment with glitazones effectively reduced the levels of this enzyme." (PMID 24684779, 2014). "The relative mRNA levels of MMP-9 were detected by real-time RT-PCR analysis at 1, 4, 8, and 12 weeks after the onset of diabetes." (PMID 23671886, 2013). "Matrix metalloproteinase-9 (MMP-9), an enzyme which is proapoptotic in the development of diabetic retinopathy, is also epigenetically modified in the retina in diabetes." (PMID 24286082, 2013). "A strong relation between ERK1/2 activation and MMP-9 is observed in various pathological conditions including diabetes." (PMID 23671886, 2013). "In order to assess the specificity of the uPAR deletion in preventing MMP9 activation, we determined the effects of diabetes on MMP9 expression by quantitative PCR." (PMID 23951261, 2013). "For example, suppression of SIRT1 has been shown to increase Mφ infiltration into inflamed tissues in mouse models of diabetes and colitis, perhaps by increased NFkB activity and increased expression of MMP9." (PMID 24386389, 2013). "It has been postulated that diabetes negatively impacts the tendon ECM profile not only due to AGE formation but also as a result of increased MMP-9 and MMP-13 expression in tendon cells." (PMID 23981230, 2013). "Kumari and colleagues used this model to show that diabetes increases the activity of matrix metalloproteinase-9 (MMP-9) following MCAO." (PMID 23344061, 2013). "We also detected a trend of increase (P > 0.05) in the number of MMP-9-positive cells in diabetic group after 12 months of diabetes induction." (PMID 22611374, 2012). "Compared to the highest group and after adjustment for smoking, gender, BMI, age, diabetes, season and activated vitamin D treatment, the log MMP-9 concentration was greater in the lowest 25(OH)D group (P = 0.046)." (PMID 21600051, 2011). "Increased production of Matrix Metalloproteinase-2 (MMP-2) and Matrix Metalloproteinase-9 (MMP-9) in diabetes leads to degradation of extra cellular matrix in blood vessels and enhance complications of diabetes." (PMID 21593984, 2008). "We then compared these findings of alloxan-induced diabetes in MMP-9 knockout mice to alloxan-induced diabetes in the wild type." (PMID 15985157, 2005).
diabetes (continued). "This study demonstrates that serum MMP-9 levels are significantly elevated in individuals with chronic wounds, particularly among those with diabetes mellitus, aligning with findings from previous studies that utilized wound fluid and tissue biopsies for MMP-9 estimation." (PMID 41189831, 2025). "In diabetes, hyperglycemia enhances MMP9 secretion from large-vessel endothelial cells." (PMID 41516018, 2025). "The binding we observed may be that DNJ-TFs interfere with the protease function of MMP9 by occupying the zinc ion-binding domain or other key regions, thereby delaying the progression of diabetes." (PMID 41515216, 2025). "Our study suggests that MMP9 may be a potential biomarker for the earlier detection of carotid artery and coronary artery plaques in patients with diabetes." (PMID 38660518, 2024). "In line with the information in the literature, our study data show that the combination of ellagic acid and carnosic acid increases collagen synthesis in diabetic wounds and contributes to the establishment of collagen balance by suppressing MMP-9 levels that increase with diabetes." (PMID 39758844, 2024). "An upregulation of MMP-9 is associated with a disruption of the blood–brain barrier (BBB) and neuroinflammation, which is a risk factor for brain inflammatory disorders, neurodegenerative diseases, cardiovascular diseases, and diabetes." (PMID 38275397, 2024). "Exploring potential therapeutic targets like MMP-9 and using natural ingredients like P. crocatum in combination with other diabetes-friendly products may provide promising avenues for preventing DFUs and improving the outcomes for patients with diabetes." (PMID 38422498, 2024). "Excessive MMP9 production results in the degradation or remodeling of the extracellular matrix, leading to compromised vascular supply to sensory nerve fibers, which, in turn, induces peripheral nerve dysfunction in individuals with diabetes." (PMID 38390212, 2024). "As most matrix metalloproteinases are elastase-type endopeptidases, mainly MMP2 and MMP9, the dynamic balance of MMPs/TIMPs maintains the stabilization of the ECM; however, diabetes disturbs this balance and causes atherosclerotic plaque disruption, myocardial fibrosis, and remodeling." (PMID 36865917, 2023). "Other variables with a p value under 0.20 in the univariate analysis and which were included in the multivariate analysis were CD cardiac form, sex, body mass index, diabetes mellitus, LV aneurysm, MMP-9, use of either ACE inhibitor or ARB, use of warfarin, and use of amiodarone." (PMID 38126526, 2023). "Caffeic acid and the ethanolic extract of spent coffee grounds could potentially act as dual inhibitors targeting DPP-4 and MMP-9 as alternative treatments for type 2 diabetes mellitus and diabetic foot ulcers." (PMID 37894660, 2023). "In Cox regression analysis at baseline, established cardiovascular risk factors, such as diabetes and smoking, along with low GSM score and high CAVI, and MMP-9 emerged as independent predictors of MACE in patients with carotid atherosclerosis requiring revascularization." (PMID 37759829, 2023). "Diabetes wounds treated by MMP-9-siRNA exhibit reduced MMP-9 levels." (PMID 36339630, 2022). "Interestingly, Notch signaling can directly regulate Mmp9 expression by enhancing its promoter activity, as shown in a model of pancreatic cancer and a model of wound healing in diabetes." (PMID 36355906, 2022). "The prognosis of patients with AIS at 90-days after IVT was used as the dependent variable, and age, smoking, hypertension, diabetes, coronary artery disease, hyperlipidemia, atrial fibrillation, IL-6, MMP-9, ADAMTS13, TRX, TNC, and GSN were considered independent variables." (PMID 36127663, 2022). "MMP-9 in humans has three fibronectin type II domains, which are collagen-binding domains, which is especially interesting given that several collagen-binding miRNAs are increased in diabetes." (PMID 35327470, 2022).